PLCB3 (phospholipase C beta 3)
Description:
Catalyzes the production of the second messenger molecules diacylglycerol (DAG) and inositol 1,4,5-trisphosphate (IP3). Key transducer of G protein-coupled receptor signaling: activated by G(q)/G(11) G alpha proteins downstream of G protein-coupled receptors activation. In neutrophils, participates in a phospholipase C-activating N-formyl peptide-activated GPCR (G protein-coupled receptor) signaling pathway by promoting RASGRP4 activation by DAG, to promote neutrophil functional responses (By similarity). In conjunction with OSBPL2, it may contribute to the control of keratinocyte proliferation and differentiation, probably through the regulation of the ERK pathway and the cell cycle.
Synonyms: SMDCD
Tractability: Small molecule: a structure with a bound ligand is known; it has a binding pocket of medium quality. PROTAC: ubiquitination databases record sites on it; its protein half-life has been measured.
Target class: Enzyme
Gene: Protein-coding gene on chromosome 11 (64,251,514 to 64,269,395, forward strand). Ensembl gene ENSG00000149782.
Subcellular location: Cytoplasm; Membrane; Nucleus
Subcellular location (Human Protein Atlas): Golgi apparatus; Nucleoplasm
Pathways (Reactome):
Signal Transduction: Ca2+ pathway; G alpha (q) signalling events; G beta:gamma signalling through PLC beta; PLC beta mediated events
Metabolism: Acetylcholine regulates insulin secretion; Fatty Acids bound to GPR40 (FFAR1) regulate insulin secretion; Synthesis of IP3 and IP4 in the cytosol
Neuronal System: Presynaptic function of Kainate receptors
Gene Ontology:
Molecular function: cadherin binding; calmodulin binding; G-protein beta-subunit binding; G-protein gamma-subunit binding; molecular adaptor activity; molecular function activator activity; phosphatidylinositol-4,5-bisphosphate phospholipase C activity; protein binding; phosphatidylinositol phospholipase C activity; phospholipase C activity; calcium ion binding; phosphoric diester hydrolase activity
Biological process: phosphatidylinositol metabolic process; phospholipase C-activating G protein-coupled receptor signaling pathway; phospholipase C-activating serotonin receptor signaling pathway; regulation of systemic arterial blood pressure; G protein-coupled receptor signaling pathway; phosphatidylinositol-mediated signaling; release of sequestered calcium ion into cytosol; intracellular signal transduction; lipid catabolic process; lipid metabolic process; signal transduction
Cellular component: cytoplasm; cytoplasmic side of membrane; nucleoplasm; postsynaptic cytosol; protein-containing complex; cytosol; membrane; nucleus
Genetic constraint (gnomAD): Loss-of-function variants: 54 observed, 144.62 expected, observed/expected ratio (o/e) 0.37, 90% interval 0.3 to 0.47. The upper end of that interval is the gene's LOEUF score, 0.47, which puts it in group 2 of 6, group 1 being the genes least tolerant of losing a copy. Missense variants: 1,201 observed, 1,608.3 expected, observed/expected ratio (o/e) 0.75, 90% interval 0.71 to 0.78. Synonymous variants: 691 observed, 663.87 expected, observed/expected ratio (o/e) 1.04, 90% interval 0.98 to 1.11.
Homologues: Orthologues: chimpanzee PLCB3 (99% identical), dog PLCB3 (93% identical), mouse Plcb3 (92% identical), guinea pig PLCB3 (92% identical), pig PLCB3 (91% identical), rat Plcb3 (91% identical), macaque PLCB3 (88% identical), tropical clawed frog plcb3 (66% identical), zebrafish plcb3 (57% identical), Drosophila melanogaster Plc21C (41% identical). Paralogues in human: PLCB1 (54% identical), PLCB2 (44% identical), PLCB4 (36% identical), PLCE1 (24% identical), PLCH2 (23% identical), PLCH1 (23% identical), PLCG2 (21% identical), PLCL2 (21% identical), PLCG1 (21% identical), PLCD4 (20% identical), PLCL1 (20% identical), PLCD1 (20% identical), and 2 more.
Diseases named in the same sentence as PLCB3 in open-access papers:
PLCB3 is named in the same sentence as 44 diseases in open-access papers, as found by Europe PMC text mining. Sharing a sentence is not in itself a finding about the gene and the disease. The quoted sentences say what the papers report.
lymphoma (4 papers, 2011 to 2021). A malignant (clonal) proliferation of B- lymphocytes or T- lymphocytes which involves the lymph nodes, bone marrow and/or extranodal sites. "PLCβ3-deficiency in mice leads to lymphoma and other tumors." (PMID 26497576, 2015).
leukemia (3 papers, 2021 to 2023). A malignant (clonal) hematologic disorder, involving hematopoietic stem cells and characterized by the presence of primitive or atypical myeloid or lymphoid cells in the bone marrow and the blood. "In line with our work, it has recently been described that T-ALL and leukemia stem cells highly express the oxysterol-binding protein (OSBP)-related protein 4 ORP4L, which acts as an adaptor/scaffold assembling CD3ε, Gαq/11, and PLCβ3 into a complex that activates PLCβ3." (PMID 33440859, 2021). "Thus, we concluded the AKT activity is not dependent on PLCβ3 in this leukemia cell type." (PMID 35906240, 2022).
lung cancer (3 papers, 2022 to 2025). A malignant neoplasm involving the lung. "High expression of PLCB3 mRNA has been shown to be associated with poor survival in non–small cell lung cancer patients." (PMID 35227895, 2022). "DNAm modifications of MAPK10, PLCG1, PLCβ3 and PIK3R2 genes were consistently linked between the lung and blood samples, suggesting their pivotal role in radon-induced lung cancer." (PMID 40725119, 2025). "The elimination of ACKR2 abolished the CXCL14-promoted phosphorylation of PLCβ3, PKCα, and c-Src and lung cancer cells." (PMID 37056937, 2023). "This is inconsistent with the mechanism of gene silencing caused by promoter hypermethylation, implying alternate mechanisms besides DNAm could regulate PLCβ3 expression in lung cancer." (PMID 40725119, 2025). "However, the function of PLCβ3 in tumors seems to be controversial in lung cancer." (PMID 40725119, 2025). "The DNAm episignatures of MAPK10, PLCG1, PLCβ3 and PIK3R2 have a significant influence on radon-induced lung cancer." (PMID 40725119, 2025). "Pretreatment with U73122 and GF109203X suppressed c-Src phosphorylation activated by CXCL14 confirmed c-Src-dependent PLCβ3 and PKCα activation mediates CXCL14-induced cell migration in lung cancer cells." (PMID 37056937, 2023). "In addition, radon exposure promoted lung cancer development in the genetic engineering mouse model (GEMM), accompanied by decreased MAPK10 and increased PLCG1, PLCβ3, and PIK3R2 with mRNA and protein levels." (PMID 40725119, 2025). "In the present study, radon exposure induced PLCβ3 promoter hypermethylation, which was significantly correlated in lung tissue and blood, and its RNA and protein levels were significantly increased in lung tissue of KRASG12D lung cancer mice." (PMID 40725119, 2025). "Furthermore, the inhibition of PLCβ3, PKCα, and c-Src phosphorylation reversed CXCL14-induced transcriptional activity of NF-κB in lung cancer cells." (PMID 37056937, 2023). "Moreover, transfection of ACKR2 siRNA prevented CXCL14-activated PLCβ3, PKCα, and c-Src phosphorylation, indicating that CXCL14 promoted lung cancer cell migration and EMT through activation of ACKR2/PLCβ3/PKCα/c-Src signaling pathway." (PMID 37056937, 2023). "Additionally, ACKR2 was involved in CXCL14-triggered phospholipase Cβ3 (PLCβ3), protein kinase Cα (PKCα), and proto-oncogene c-Src signaling pathway and subsequently upregulated nuclear factor κB (NF-κB) transcription activity leading to EMT and migration of lung cancer cells." (PMID 37056937, 2023).
myeloproliferative disease (3 papers, 2018 to 2023). "In hematopoietic stem cells (HSCs), loss of PLCβ3 led to STAT5 hyperactivation, thereby increasing the number of HSCs with a myeloid differentiation ability and leading to the development of myeloproliferative neoplasms in PLCβ3-KO mice." (PMID 37371495, 2023).
atherosclerosis (2 papers, 2022 to 2025). A disease characterized by the build-up of fatty material and calcium deposition in the arterial wall resulting in partial or complete occlusion of the arterial lumen. "Pathway analysis indicated that PLCB3 is associated with lipid and atherosclerosis pathways, the NOD-like receptor signaling pathway, and the NF-κB signaling pathway, all of which are essential for recognizing pathogens and initiating inflammatory responses." (PMID 40892863, 2025). "A total of 6 genes were enriched in the lipid and atherosclerosis signaling pathway (CAMK2B, VAV3, PLCB3, NFATC3, TNFRSF10B, and BCL2L1), and these genes were regulated by tRF-60:76-Val-AAC-1-M5." (PMID 36247465, 2022).
atopic dermatitis (2 papers, 2023 to 2024). "Notably, both the PLCB3 gene and a single nucleotide polymorphism (rs792789 allele A) linked to CD and atopic dermatitis maps to human chromosome 11q13." (PMID 38891118, 2024).
Ewing sarcoma (2 papers, 2000 to 2019). A small round cell tumor that lacks morphologic, immunohistochemical, and electron microscopic evidence of neuroectodermal differentiation. "As also reported, PLCB2 and PLCB3 are likely involved in the proliferation of Ewing's sarcoma cells." (PMID 31080817, 2019).
Alzheimer disease (1 paper, 2022). A progressive, neurodegenerative disease characterized by loss of function and death of nerve cells in several areas of the brain leading to loss of cognitive function such as memory and language. "The pathways related to neurodegenerative disease, such as Alzheimer’s disease and Huntington’s disease, were also enriched with two essential DEPs (GAPDH, PLCB3 and SP1, PLCB3, respectively)." (PMID 35741576, 2022).
anemia (1 paper, 2024). A reduction in the number of red blood cells, the amount of hemoglobin, and/or the volume of packed red blood cells. "DSS-treated Plcb3−/− mice exhibited bloody stool and severe anemia." (PMID 38891118, 2024).
brain tumors (1 paper, 2022). "In addition, four other TSGenes are expressed at two- to eight-fold lower levels in T-ALL compared to brain tumors and/or B-ALL samples: NEDD4L, PLCB3, APC and ZMYND11." (PMID 35401501, 2022).
breast carcinoma (1 paper, 2021). "Further analyses showed that PCI-24781 inhibited Gαq-PLCβ3-mediated calcium signaling by activating the expression of regulator of G-protein signaling 2 (RGS2) to reduce cell proliferation, metastasis, and differentiation, resulting in cell death in breast cancer." (PMID 33500709, 2021).
colorectal cancer (1 paper, 2024). A primary or metastatic malignant neoplasm that affects the colon or rectum. "With a hazard ratio (HR) of 2.75 and a confidence interval (CI) ranging from 1.61 to 4.68, PLCB3 exerts the most pronounced impact on the outcomes of colorectal cancer (CRC) patients." (PMID 38724565, 2024). "Furthermore, cetuximab suppressed Wnt/β-catenin pathway to modulate PLCB3 expression, thus inhibiting colorectal cancer progression." (PMID 38724565, 2024).
corneal dystrophy (1 paper, 2023). The term corneal dystrophy embraces a heterogeneous group of bilateral genetically determined non-inflammatory corneal diseases that are usually restricted to the cornea. "As an example, whole genome homozygosity mapping on a family with two cousins affected with a novel recessive phenotype of spondymetaphyseal dysplasia with corneal dystrophy (OMIM# 618961) succeeded in linking the condition to a variant in the PLCB3 gene." (PMID 37214420, 2023).
cystic fibrosis (1 paper, 2019). Autosomal recessive disorder caused by pathogenic variants in the CFTR gene (cystic fibrosis transmembrane conductance regulator), which encodes a chloride and bicarbonate channel expressed in epithelial cells, and follow the diagnosis criteria. "PLCB3 also regulates the cystic fibrosis inflammatory response by amplifying the expression and release of IL-8 and recruiting neutrophils to CF airways." (PMID 31737645, 2019).
dermatitis (1 paper, 2015). An inflammatory process affecting the skin. "Both spontaneous and allergen-induced dermatitis in Plcb3−/−mice required the receptor for TSLP." (PMID 26379670, 2015).
inflammatory bowel disease (1 paper, 2024). A spectrum of small and large bowel inflammatory diseases of unknown etiology. "Moreover, ATAC-seq analysis followed by pathway analysis using clusterProfiler revealed that the Wnt signaling pathway, inflammatory bowel disease pathway, calcium signaling pathway, and tight junction pathway were in the top 30 pathways that were different between WT and Plcb3−/− cells." (PMID 38891118, 2024).
lung disease (1 paper, 2020). "Single Nucleotide Polymorphisms (SNP) genetic study with the progression of CF lung disease severity, identify from a panel of 135 genes of immune response the association of c.2534C>T (p.S845L) variant of PLCB3 with a mild progression of pulmonary disease in CF." (PMID 32849500, 2020). "The role of PLCB3 in amplifying the expression and release of IL-8 during pathogen infection, through the regulation of intracellular Ca2+ transients, is associated with the severity and progression of CF lung disease." (PMID 32849500, 2020).
multiple endocrine neoplasia type 1 (1 paper, 2019). An autosomal dominant tumor predisposition syndrome caused by pathogenic variants in the MEN1 gene, characterized by an increased risk of tumors of the parathyroid glands, pituitary gland, and foregut neuroendocrine tumors (most commonly pancreatic islet cells). "For instance, PLCB3 gene expression is lost in multiple endocrine neoplasia type 1 and lowered in abnormal platelet aggregation." (PMID 31080817, 2019).
myocardial infarction (1 paper, 2023). Gross necrosis of the myocardium, as a result of interruption of the blood supply to the area, as in coronary thrombosis. "Similarly, exosomes from human umbilical cord-derived MSCs were reported to attenuate mouse myocardial infarction injury by enhancing M2 macrophage polarization through exosomal miR-24-3p-mediated Plcb3/NF-κB signaling pathway." (PMID 37242732, 2023).
neuroendocrine tumor (1 paper, 2025). "Prior research indicates that PLCβ3 transcripts are lost in certain tumor tissues and neuroendocrine tumor cell lines." (PMID 40725119, 2025).
prostate carcinoma (1 paper, 2012). A carcinoma that arises from epithelial cells of the prostate gland. "This increase of prostate cancer cell migration and invasion was not only a result of PLCβ3 activation by CXCR3A, but also required downregulation of the strength of inhibitory signal via CXCR3B." (PMID 22236567, 2012).
prostate tumors (1 paper, 2016). "Compared to the primary prostate tumors, mRNA level of NFKBIA, DUSP6, PLCB3, and SMAD4 are lower in metastatic prostate tumors, while mRNA level of RELA and SNAI1 exhibit opposite trend." (PMID 27191743, 2016). "On the other hand, mRNA levels of ROR2, NFKBIA, DUSP6, PLCB3, and SMAD4 are lower in metastatic prostate tumors as compared to primary prostate tumors." (PMID 27191743, 2016).
schizophrenia (1 paper, 2021). A major psychotic disorder characterized by abnormalities in the perception or expression of reality. "We noticed four of the DEGs (PLD2, PLCB3, PLAAT4, RPS27) involved in these pathways were also differentially expressed in the brain of patients with schizophrenia." (PMID 34630179, 2021).
ulcerative colitis (1 paper, 2024). An inflammatory bowel disease involving the mucosal surface of the large intestine and rectum. "In the GSE57945 dataset, PLCB3 mRNA expression in ileal biopsy samples was lower in pediatric CD patients, especially those with deep ulcers, but not in patients with ulcerative colitis." (PMID 38891118, 2024). "Consistent with these previous studies and our current data with Plcb3−/− mice, we found reduced expression of PLCB3 and altered expression of PLCB3-regulated signature genes in ileal CD, but not in other CD subtypes or ulcerative colitis." (PMID 38891118, 2024). "Data in GSE83448 also showed reduced PLCB3 mRNA expression in adult ileal CD patients and data in GSE179285 showed reduced PLCB3 mRNA more strongly in inflamed than in uninflamed terminal ileum of adult CD, but not in colonic CD or ulcerative colitis patients." (PMID 38891118, 2024).
tumor (11 papers, 2000 to 2025). "Among these genes, NLRC5 and PLCB3, known for their involvement in ccRCC progression and tumor immunity, were also identified." (PMID 40740488, 2025). "As PLCβ3 interacts significantly with calcium signaling, it suggests that methylation may regulate PLCβ3 pathway in tumor." (PMID 40725119, 2025). "Concurrently, our analysis of the TCGA database demonstrated elevated PLCB3 expression levels within COAD tumor tissues, suggesting that this gene may function as an oncogene." (PMID 38724565, 2024). "When PLCβ3 is introduced into neuroendocrine cell lines that lack its expression, it can reduce tumor phenotypes and influence the gene regulation of human mismatch repair proteins, suggesting its potential role as a tumor suppressor in neuroendocrine tumorigenesis." (PMID 40725119, 2025). "TRG with higher amplification frequencies were found to have higher mRNA expression levels in cancerous tissues than in normal tissues, such as ILIRAP, PIK3CA, PPPICA, and PLCB3, suggesting that TRG may be tumor heterogeneous in normal versus cancerous cervical samples." (PMID 38784033, 2024).
cancer (4 papers, 2021 to 2023). A tumor composed of atypical neoplastic, often pleomorphic cells that invade other tissues. "Phospholipase C beta 3 (PLCB3), which encodes a member of the phosphoinositide phospholipase C beta enzyme family, was found to be one of the critical altered genes involved in aristolochic acid–induced gastric benign or malignant tumors." (PMID 34277706, 2021). "The expression of NUBP2, PLCB3, PPP1CA, TBCB, and UBE2C were positively correlated with PPP1R14B in the majority of cancer types." (PMID 34858479, 2021).
adenocarcinoma (2 papers, 2019 to 2025). A common cancer characterized by the presence of malignant glandular cells. "High mRNA expression levels of PLCB1, PLCB2, and PLCB3 were significantly associated with poor overall survival (OS) of all NSCLC patients and significantly associated with poor prognosis of adenocarcinoma." (PMID 31080817, 2019).
infection (2 papers, 2008 to 2021). The state of being infected such as from the introduction of a foreign agent such as serum, vaccine, antigenic substance or organism. "The modules that were co-up-regulated in CD4 and CD8 cells after infection included IRF9, IRF7, PLCB3, CXCL3, and TXN, among others." (PMID 34603402, 2021). "Lentiviral infection is used to introduce small hairpin RNAs to interfere with the translation of the key signaling proteins GRK2, Gαi2, Gαq, PLCβ3 and PLCβ4." (PMID 18818727, 2008).
PLCB3 also shares sentences with these, for which no sentence is quoted: pancreatic cancer (2 papers); autoimmune conditions (1); Burkitt lymphoma (1); chronic myelomonocytic leukemia (1); colitis (1); gastric cancer (1); Huntington disease (1); Hypertension (1); melanoma (1); myeloproliferative neoplasm (1); neurodegenerative disease (1); Obesity (1); peripheral nerve injury (1); Pruritus (1); spinocerebellar ataxia (1); type 2 diabetes (1).